CLDN4 (claudin 4)
Diseases named in the same sentence as CLDN4 in open-access papers (continued):
Sharing a sentence is not in itself a finding about the gene and the disease.
ovarian carcinoma (continued). "The results showed that the effect of claudin-3 or claudin-4 on the sensitivity of ovarian cancer cells to cisplatin is mediated in part by the regulation of the expression of the copper and cisplatin influx transporter CTR1." (PMID 24009024, 2013). "Especially, CPE is effective in chemoresistant/recurrent ovarian cancer based on the high expression of claudin-3 and claudin-4 in chemoresistant/recurrent ovarian tumors." (PMID 24009024, 2013). "A recent study showed that claudin-4 promotes the motility of breast or ovarian cancer cells through interactions of its second extracellular loop with extracellular matrix proteins." (PMID 24009024, 2013). "Taken together, our results suggest that CLDN3 and CLDN4 serve to maintain the expression of E-cadherin which acts as a central modulator of EMT in the ovarian cancer cells via a pathway involving PI3K/Akt and EMT transcription factor Twist." (PMID 23805314, 2013). "Both claudin-3 and/or claudin-4 genes were found to be highly expressed in all primary ovarian carcinomas when compared to normal ovarian epithelial cells." (PMID 23685873, 2013). "Claudin-4 expression was significantly greater in ovarian cancer tissue from chemo-resistant patients compared to chemo-sensitive patients." (PMID 23685873, 2013). "One large study found that claudin-4 was expressed in nearly 70% of the ovarian cancer tissues examined and was differentially expressed across ovarian cancer subtypes, with the lowest expression noted in clear cell ovarian carcinomas." (PMID 23685873, 2013). "TJ formation and cell adhesion is impaired in claudin-3 and claudin-4 knockdown ovarian cancer cells." (PMID 24009024, 2013). "In contrast to the roles of claudin-3 and claudin-4 in ovarian cancer cells, claudin-1 promotes EMT in human liver cells, supporting the notion that the role of claudins in EMT is tissue-specific." (PMID 24009024, 2013). "For example, phosphorylation of claudin-3 and claudin-4 by PKA or PKC increases paracellular permeability in ovarian cancer cells via mislocalization of claudins." (PMID 24009024, 2013). "Claudin-4 promotes the production of factors that stimulate angiogenesis both in vitro and in vivo, suggesting its pro-angiogenic role in ovarian cancer." (PMID 24009024, 2013). "First, knockdown of claudin-4 expression in ovarian cancer cells delayed spheroid formation, suggesting the involvement of claudin-4 in the regulation of spheroid formation." (PMID 24009024, 2013). "The present observations raise the possibility of exploiting CLDN3 and CLDN4 as potential biomarkers for ovarian cancer progression and highlight maintenance of E-cadherin levels as a target for therapeutic intervention." (PMID 23805314, 2013). "Recently, claudin-4 was detected in the peripheral circulation of ovarian cancer patients, further supporting its usefulness as a biomarker." (PMID 24009024, 2013). "Thirty-three out of the 43 cases (76.7%) of patients with ovarian cancer examined had positive claudin-4 expression with a significant shorter survival noted in the claudin-4 positive versus claudin-4 negative group." (PMID 23685873, 2013). "As in ovarian cancer cells, PKCα activation results in the mislocalization of claudin-4 along with decreased tight junction barrier integrity in human pancreatic cancer cells." (PMID 24009024, 2013). "Among claudin proteins, claudin-3 and claudin-4 have been shown to be highly upregulated in ovarian carcinoma compared to normal ovarian surface epithelium in several studies." (PMID 24009024, 2013). "A Japanese research group reported similar results showing that claudin-4 expression was higher in ovarian cancer tissue from platinum-based chemo-resistant patients versus chemo-sensitive patients." (PMID 23685873, 2013).
ovarian carcinoma (continued). "We have evaluated the levels of claudin 4 RNA and protein in ovarian cancer tissues and cell lines using RT-PCR, qRT-PCR, Western immunoblotting, and immunohistochemistry, in order to assess the potential of claudin 4 as an ovarian cancer biomarker." (PMID 21541062, 2011). "Claudin 4 was expressed in nearly 70% of the ovarian cancer tissues examined and was differentially expressed across ovarian cancer subtypes, with the lowest expression in clear cell subtype." (PMID 21541062, 2011). "Claudin 4 is a cellular adhesion molecule that is frequently overexpressed in ovarian cancer and other epithelial cancers." (PMID 21541062, 2011). "In this study, we sought to validate the overexpression of claudin 4 that we previously observed in ovarian cancer tissues in our gene microarray experiments." (PMID 21541062, 2011). "We examined claudin 4 expression in ovarian cancer tissues and cell lines, as well as by immunohistochemical staining of tissue microarrays (TMAs; n = 500), spheroids present in patients’ ascites, and spheroids formed in vitro." (PMID 21541062, 2011). "We used q-RT-PCR assays to get highly sensitive measurements of claudin-3 and claudin-4 CPE receptor expression in normal tissue cells and primary human tumors derived from patients harboring chemotherapy-resistant ovarian carcinomas." (PMID 20598131, 2010). "Claudin-3 and claudin-4 are tight junction proteins overexpressed in ovarian carcinomas, the most lethal gynecologic malignancy in the United States." (PMID 20598131, 2010). "The data presented here show that ovarian cancer-derived exosomes contain high levels of the membrane protein claudin-4." (PMID 19619303, 2009). "A follow up study with a more sensitive detection strategy and a larger number of ovarian cancer patients (with tumors of various stages and grades) tested for circulating claudin-4 will help to clarify these issues." (PMID 19619303, 2009). "Based on these figures, claudin-4 has a sensitivity of 51% (32/63) and specificity of 98% (49/50) for the detection of ovarian cancer." (PMID 19619303, 2009). "In particular, we and others have shown that claudin-3 and claudin-4 are elevated in ovarian cancer." (PMID 19619303, 2009). "Because of the known limitations of CA125 for the detection of early ovarian cancer, the finding that claudin-4 can possibly detect early cases of ovarian cases is particularly intriguing." (PMID 19619303, 2009). "Our work shows for the first time that claudin-4 can be released from ovarian cancer cells and can be detected in the peripheral circulation of ovarian cancer patients." (PMID 19619303, 2009). "Among the 63 ovarian cancer patients, 23 samples demonstrated a strong claudin-4 band with 9 additional samples exhibiting low to moderate levels." (PMID 19619303, 2009). "Several plasma samples from patients with ovarian cancer exhibited high levels of claudin-4, while blood from control individuals showed very low or undetectable levels." (PMID 19619303, 2009). "More recently, overexpression of claudin-4 in ovarian cancer was found to be partly regulated by a small region in the claudin-4 promoter-containing Sp1 sites." (PMID 18648369, 2008). "The expression of Claudin-4 is upregulated in ovarian cancer, gastric adenocarcinoma and colorectal cancer." (PMID 18781153, 2008). "Previous studies have shown that Claudin-1, Claudin-3, Claudin-4 and Claudin-7 proteins are highly expressed in ovarian carcinoma." (PMID 18781153, 2008). "In a study conducted in ovarian tissue, Hough and coworkers found that expression of CLDN3 and CLDN4 protein was undetectable in normal ovarian cells and highly expressed on the membranes of ovarian carcinoma cells." (PMID 15743508, 2005). "SAGE (serial analysis of gene expression) demonstrated that, of differentially upregulated mRNAs, CLDN3 and CLDN4 were among the six most upregulated in primary ovarian carcinoma cells." (PMID 15743508, 2005).
ovarian carcinoma (continued). "Thus, CLDN3 and CLDN4 play multifaceted roles in ovarian cancer, sustaining an epithelial phenotype and promoting survival, invasion, and therapy resistance." (PMID 40687428, 2025). "Future prospective, multicenter studies integrating Claudin-4 expression with genomic and transcriptomic profiling could further refine its prognostic and predictive potential in epithelial ovarian cancer." (PMID 41464164, 2025). "Additionally, several studies underscore the potential clinical significance of claudin-4 in the treatment and prognosis of ovarian cancer." (PMID 39625235, 2025). "Moreover, in ovarian cancer cells, CLDN4 was found to interact with both α- and β-tubulins, thereby affecting the structure and dynamic state of the microtubules and reducing apoptotic responses to microtubule-targeting agents (MTAs), including paclitaxel." (PMID 40943068, 2025). "Claudin-4 overexpression resulted in fewer cells in the S-phase, suggesting that this protein may act as a brake, delaying ovarian cancer cells’ entry into the S-phase." (PMID 39625235, 2025). "In this study, we aimed to determine the influence of claudin-4 on cell-cycle progression and nuclear architecture, and how its regulation may lead to changes in genomic instability and therapy resistance in ovarian cancer cells." (PMID 39625235, 2025). "Claudin 4 is overexpressed in exosomes derived from BG-1 ovarian cancer cell line and in serum from ovarian cancer patients; this protein controls the permeability of the paracellular barrier and increases metastasis potential and its suppression reduces invasion and metastasis." (PMID 38796525, 2024). "A down-regulation of CLDN4 makes ovarian cancer cells vulnerable to Taxol and Carboplatin." (PMID 38238671, 2024). "CLDN4 expression was not linked with OS in patients with ovarian cancer who had nonlymphatic invasion, early clinical stage, and early histologic grade." (PMID 37057131, 2023). "In addition, we carried out subgroup analysis, which revealed that elevated CLDN4 expression demonstrated a significant correlation in both younger and older ovarian cancer patients." (PMID 37057131, 2023). "Furthermore, CLDN3 and CLDN4 impeded EMT in ovarian carcinoma through the activation of the PI3K/Akt pathway, in line with CLDN7-mediated inhibition of cell migration and invasion through the ERK/MAPK signaling pathway in human lung cancer cells." (PMID 36672179, 2023). "Additionally, Claudin-4 positive human ovarian carcinoma cells experienced a 6.7-fold elevation in toxicity when treated with a fusion of recombinant c-CPE and tumor necrosis factor (TNF) than with TNF alone." (PMID 36077843, 2022). "In addition, claudin-4 protein is released by ovarian cancer cells and is highly expressed in the peripheral circulation of of ovarian cancer patients." (PMID 36741380, 2022). "Moreover, the protein CLDN4 has been identified in circulating exosomes derived from ovarian cancer cells, allowing the possibility of early ovarian cancer diagnosis." (PMID 35008322, 2021). "In metastasizing and cisplatin-resistant ovarian cancer cells, claudin-4 or-7/EpCAM/CD82 complex has been detected and the question arose whether the interactions were direct or indirect." (PMID 32091301, 2020). "Knockdown studies in ovarian cancer cells suggest that this positive effect of claudin-4 overexpression may be due to its ability to sustain the expression of E-cadherin and limit β-catenin signaling." (PMID 32414951, 2020). "Similarly, claudin-4 accelerates cell migration and invasion in ovarian tumor cell lines, in support of this, peptide-mediated silencing of claudin-4 in ovarian cancer cells exhibited lower tumor burden." (PMID 31861759, 2019). "Both in vitro and in vivo studies in ovarian cancer observed that claudin-4 promotes the angiogenesis by inducing the production of angiogenic factors such as IL-8, suggesting the pro-angiogenic role of claudin-4 in ovarian cancer." (PMID 30728783, 2018).
ovarian carcinoma (continued). "Importantly, EVs derived from ovarian cancer patients positive for claudin-4 are also positive for CA125." (PMID 30322133, 2018). "Moreover, CLDN4 seemed to be involved in the regulation of spheroid formation, since knockdown of CLDN4 expression delayed spheroid formation in ovarian cancer cells." (PMID 28545541, 2017). "Whereas, the transcriptional activity of CLDN3 and CLDN4 is increased in ovarian cancer." (PMID 29221203, 2017). "Exosomes from ovarian cancer patient plasma contain Claudin-4." (PMID 29262670, 2017). "A recent study also demonstrated that both CLDN3 and CLDN4 regulated EMT in ovarian cancer cells." (PMID 25277196, 2014). "In fact, CLDN3 and CLDN4 are among the most highly up-regulated genes found in ovarian cancers." (PMID 23805314, 2013). "A recent study by a Japanese group reported that ovarian cancer tissues from platinum-resistant patients have higher levels of claudin-4 expression than those from chemosensitive patients, and suppression of claudin-4 increased the sensitivity of ovarian cancer cells to cisplatin." (PMID 24009024, 2013). "It is important to note that the upregulation of claudin-3 and claudin-4 expression in ovarian cancer is based on the hypothesis that ovarian cancer arises from normal ovarian surface epithelium." (PMID 24009024, 2013). "By contrast, claudin-4 overexpression in ovarian cancer is associated with DNA hypomethylation, whereas gene amplification is not related to claudin-4 expression." (PMID 24009024, 2013). "Therefore, further comprehensive studies are necessary to elucidate the exact role of claudin-3 and claudin-4 in ovarian cancer." (PMID 24009024, 2013). "Claudin-3 and claudin-4 are highly overexpressed in ovarian cancer including serous carcinoma compared to normal ovarian tissues, and their expression is also upregulated in several other malignancies, including breast, gastric, pancreatic, prostate and uterine cancers." (PMID 24009024, 2013). "Here again multiple sublethal doses of i.p CPE proved to be an effective strategy for the eradication of claudin-4 expressing chemo-resistant ovarian cancer stem cells in mice harboring these xenografts with a 100% reduction in tumor burden in 50% of treated mice; p < 0.0001." (PMID 23685873, 2013). "Therefore, the overexpression of claudin-3 or claudin-4 has been shown to promote the progression of ovarian cancer." (PMID 24009024, 2013). "We also sought to determine whether claudin 4 overexpression could be correlated with relevant clinical outcomes using tissue microarrays comprised of 500 cases of clinically annotated ovarian cancer." (PMID 21541062, 2011). "In an effort to find novel biomarkers for ovarian cancer using gene expression profiling, we and others have identified claudin 4 as a gene that is highly overexpressed in ovarian cancer, and thus may contribute to tumor formation and metastasis." (PMID 21541062, 2011). "We previously reported in vitro characterization of a fusion protein, CPE290-319-TNF, and demonstrated that the C-terminal 30 amino acids (amino acids 290-319) of CPE could effectively target TNF to ovarian cancer cells expressing claudin-3 and claudin-4." (PMID 21303546, 2011). "On the basis of the high expression of claudin-3 and/or claudin-4 detected by RT-PCR in primary ovarian cancer cell lines we predicted that the FITC-conjugated CPE peptide may bind to ovarian tumors in vitro." (PMID 20598131, 2010). "To determine whether claudins are released in the media as free molecules or as part of larger complexes, we focused on claudin-4 and performed a series of sedimentation experiments using media from the BG-1 ovarian cancer cell line." (PMID 19619303, 2009). "While the current work establishes that claudins can indeed be present in the peripheral circulation of ovarian cancer patients, several important issues will need to be clarified in subsequent studies before claudin-4 can be considered a viable biomarker for ovarian cancer detection." (PMID 19619303, 2009).
ovarian carcinoma (continued). "Other members of the family, CLDN3 and CLDN4 are frequently overexpressed in ovarian cancer." (PMID 18211683, 2008). "In addition, it has been shown previously that overexpression of Claudin-4 promotes tumorigenecity and metastasis in ovarian cancer through the increased invasion and survival of tumour cells." (PMID 18781153, 2008). "Thus, targeting claudin-4 could reduce the required dosage of olaparib to induce cell death in ovarian cancer cells, potentially decreasing therapy resistance." (PMID 39625235, 2025). "Furthermore, because ovarian cancer cells were cultured for 7 days in the colony formation assay, we speculated that hypoxia may play a role in claudin-4–mediated resistance to olaparib." (PMID 39625235, 2025). "Consequently, to gain further insight into the potential of targeting claudin-4’s functional effects, such as those observed in cell cycle and nuclear remodeling in ovarian cancer cell survival, we evaluated the effects of CMP and FSK on enhancing olaparib efficacy in a 7-day colony formation assay." (PMID 39625235, 2025). "Therefore, claudin-4 is a potential biomarker for ovarian cancer detection." (PMID 38796525, 2024). "KM3900 was found to bind to CLDN4 on pancreatic and ovarian cancer cells but not normal cells, causing dose-dependent, antibody-dependent cellular cytotoxicity (ADCC) and complement-dependent cytotoxicity (CDC) in vitro, as well as in vivo tumor growth inhibition in mice models." (PMID 38731853, 2024). "Overexpression of CLDN4 has been reported in various cancers, such as gastric cancer, pancreatic cancer, colorectal cancer, breast cancer (especially triple-negative breast cancer), oral squamous cell carcinoma, ovarian cancer, bladder cancer, non-small cell lung cancer, and cholangiocarcinoma." (PMID 36982569, 2023). "Furthermore, claudin-3 (CLDN3) and claudin-4 (CLDN4) are overexpressed in ovarian cancer." (PMID 35665865, 2022). "Thus, we also asked, whether chemoresistance of human ovarian cancer was so correlated with EpCAM, claudin-4 and −7, and CD82 coexpression/complex formation." (PMID 32091301, 2020). "Interestingly, in addition to claudin-3 and claudin-4, claudin-6 might serve as a novel receptor for Clostridium perfinges enterotoxin in ovarian cancer." (PMID 32197343, 2020). "Similarly to claudin-3, claudin-4 is highly elevated in ovarian cancer." (PMID 32197343, 2020). "Evidences showing that low claudin-4 expression is linked to poor prognosis of patients with breast, esophageal, colon and pancreatic cancers suggest that claudin-4 expression is likely to play a tumor suppressive role in several cancers, although its role in ovarian cancer remains unclear." (PMID 24009024, 2013). "Moreover, with the exception of claudin-4, all the other claudins were upregulated in ovarian cancer effusions compared with solid tumors and that the expression of claudins-3 and -7 in pleural effusions independently predicts poor survival in ovarian cancer." (PMID 23685873, 2013). "Finally, because of its role in intercellular adhesion, and the importance of ovarian cancer spheroids in ovarian cancer metastasis and chemoresistance, we examined the expression of claudin 4 in ovarian cancer spheroids and its potential role in spheroid formation." (PMID 21541062, 2011). "The development of sensitive assays for the detection of claudin-4 in blood will be crucial in determining whether this approach can be useful, alone or in combination with other screening methods, for the detection of ovarian cancer." (PMID 19619303, 2009). "In summary, ovarian cancer exhibits a pattern of claudin upregulation (CLDN3, CLDN4, CLDN7, CLDN9) that supports tumor growth, dissemination, and chemoresistance." (PMID 40687428, 2025). "Opposite effects were observed for ovarian cancer cells, where the knockdown of CLDN3 and CLDN4 induced resistance to cisplatin by regulating the Cu transporter CTR1." (PMID 40943068, 2025).